U2 (U2 spliceosomal RNA )
Synonyms: LOC124904144
Gene: Small nuclear RNA gene on chromosome 17 (43,300,041 to 43,300,231, reverse strand). Ensembl gene ENSG00000278591.
Gene Ontology:
Molecular function: pre-mRNA branch point binding
Biological process: mRNA branch site recognition
Cellular component: U2 snRNP
Homologues: Orthologues: chimpanzee U2 (100% identical), macaque U2 (100% identical), dog U2 (99% identical), pig U2 (48% identical), rat LOC120094029 (36% identical). Paralogues in human: U2 (100% identical), RNU2-2 (96% identical), U2 (95% identical), RNU2-3P (93% identical), RNU2-4P (93% identical), RNU2-17P (90% identical), RNU2-6P (90% identical), RNU2-48P (89% identical), RNU2-52P (89% identical), RNU2-59P (89% identical), RNU2-25P (87% identical), RNU2-26P (87% identical), and 68 more.